RAC1 (Rac family small GTPase 1)
Diseases named in the same sentence as RAC1 in open-access papers (continued):
Sharing a sentence is not in itself a finding about the gene and the disease.
tumor (continued). "Because of sequence variation among the raccoon isolates, the designations 1–10 indicate the order of animal submission and which raccoon harbored which respective RacPyV; that is, RacPyV1 was found in Rac1 and was the first tumor and RacPyV discovered." (PMID 23260029, 2013). "Previous studies have shown that signaling downstream of SFKs, including activation of p120 catenin, p130cas, and their resultant Rac1 signaling, can promote tumor cell migration and invasion." (PMID 23457577, 2013). "Further work in these lines have demonstrated that knockdown of IAPs using an IAC lead to an elongated morphology in various primary and tumor cells as well as Rac1- and MAPK-dependent enhanced migration in tumor cells." (PMID 24008728, 2013). "In situ hybridization validated Rac1 transcription in some wild-type GSCs and in some GSC-like cells in tumorous germaria caused by expression of a constitutively active form of the BMP type I receptor Thickveins (TkvAct)." (PMID 22802725, 2012). "With respect to mitogen-activated protein kinases (MAPKs), ERK can also regulate the activity of Rac1, allowing the formation of cellular protrusions and thereby contributing to tumor cell motility and invasion." (PMID 22970259, 2012). "It is also well established that Rho, Cdc42 and particularly Rac1 have critical roles in experimental tumour metastasis." (PMID 22689141, 2012). "RAC1 was significantly higher and associated with poor prognosis in HER2 (ERBB2) over-expressing tumours, although the range of RAC1 expression was similar between HER2+ and HER2− tumours." (PMID 22689141, 2012). "Previously, we demonstrated that Rac1 GTPase was required for tumor cell transendothelial cell migration." (PMID 21776386, 2011). "This study reveals that Rac1 is prooncogenic in that it can alter TGF-β signalling at the R-Smad level from a tumour-suppressive towards a tumour-promoting outcome." (PMID 21624123, 2011). "Primary human tumor cells were infected with the lentivirus expressing Scr or Rac1 shRNA and subsequent Western blot analysis confirmed the effective knockdown of Rac1 protein expression in the isolated cells." (PMID 21347385, 2011). "It is widely appreciated that Rac1 acts in a prooncogenic fashion during later stages of tumour progression by promoting migration, invasion, and metastasis." (PMID 21624123, 2011). "To determine if the effect on lung colonization is related to a homing defect of the Rac1 knockdown cells in the lung, we tested the ability of the tumor cells to home to the lung tissue 48 hours after tail vein injection." (PMID 21347385, 2011). "We propose that Rac1 plays a crucial role in regulating CSC tumor initiating, metastatic activities and thus represents a novel and useful therapeutic target in NSCLA." (PMID 21347385, 2011). "In the current study, we set out to determine the individual roles of Rac1, Rac3, and RhoG in tumor cell diapedesis." (PMID 21776386, 2011). "We show that the enhanced Rac1 activity in β3-null endothelial cells is responsible, at least in part, for the elevated tumor angiogenesis and VEGF-mediated angiogenic responses in β3-null mice." (PMID 20339539, 2010). "Rac1 and Pak1 proteins were detected in tumor tissues, non-tumor tissues, metastatic lymph nodes, and normal lymph nodes (Figures." (PMID 20426825, 2010). "Previous studies in epithelial tumor cells have shown that mesenchymal cadherins (i.e. N-cadherin and cadherin 11) can promote tumor cell growth and migration via p120-mediated activation of Rac1 signaling." (PMID 21060868, 2010). "Elevated Rac1 activity promotes transformation and metastasis, and deficiency of the RacGEF, Tiam1, inhibits MMTV-Neu tumor formation." (PMID 20860838, 2010). "We analyzed Rac1 activity and Pak1 protein expression in matched sets of tumor tissue, non-tumor tissue, and metastatic lymph node tissue obtained from the surgical specimens of 108 Japanese patients with UC-UUT." (PMID 20426825, 2010).
tumor (continued). "Here we describe the role of Rac1 in tumor growth, tumor angiogenesis and VEGF-induced angiogenesis in vivo." (PMID 20339539, 2010). "The present study showed that Rac1 activity and Pak1 expression were significantly increased in primary tumors and metastatic lymph nodes compared with non-tumor tissues." (PMID 20426825, 2010). "Under the control of a tetracycline regulatable promoter, dominant negative mutants of Rac1 and Cdc42 were expressed in a human HRas-transformed, tumor derived fibroblast cell line." (PMID 20067638, 2010). "There have been few reports about the simultaneous analysis of Rac1 and Pak1 in human tumor tissues." (PMID 20426825, 2010). "Taken together, these data indicate that, while no biological effect of Rac-1 knockdown was observed in wild-type/Tie1-Cre+, the lentivirus treatment efficiently reduced expression of Rac1 in tumor blood vessels from these animals." (PMID 20339539, 2010). "In contrast, using the pSico or PDGFB-iCreER-inducible systems we have deleted Rac1, predominantly, in adult tumor or VEGF-induced neo-endothelial cells themselves, thus reducing any side effects on the whole vasculature." (PMID 20339539, 2010). "We focused our attention on the small Rho GTPase Rac1 and its effector, the p21-activated protein kinase 1 (Pak1), and the merlin tumor suppressor." (PMID 21085651, 2010). "With regard to disease-free survival of the patients who were N0 M0 at the time of nephroureterectomy (92 patients), the mean level of Rac1 activity and Pak1 expression in tumor tissue was 2.55 ± 1.62 and 2.43 ± 1.09, respectively." (PMID 20426825, 2010). "Although Pak1 is well known as a downstream effector of Rac1, there have been few simultaneous analyses of Rac1 and Pak1 expression in human tumor tissues." (PMID 20426825, 2010). "Second, pRb modulates the function of regulators of adherens junction assembly such as the small Rho GTPase Rac1 and the merlin tumor suppressor." (PMID 21085651, 2010). "Loss of E-cadherin in these tumors is associated with increased Ras, Rac1, and MAPK signaling, which induce tumor cell growth and invasion." (PMID 21060868, 2010). "Endothelial cell migration is a critical feature of tumor angiogenesis and is thought to involve both changes in integrin expression and the activity of Rho GTPases such as Rac1." (PMID 20339539, 2010). "In the present study, LVI, Pak1 activity, Rac1, pT stage, and tumor grade were related to postoperative recurrence according to univariate analysis, with both LVI and Pak1 still being significant determinants according to multivariate analysis." (PMID 20426825, 2010). "Further confirmation of the role of endothelial Rac1 in tumor growth and angiogenesis was accomplished by using a genetic ablation approach that allows conditional Rac1-deletion in an inducible-manner." (PMID 20339539, 2010). "We therefore show that in the course of transformation, up to the stage of tumor formation Rac1-dependent migration is reduced." (PMID 18253510, 2008). "This is intriguing as we previously reported increased expression of the small GTPase Rac1 in SCCs as well as the tumour promoting role of altered epidermal integrin expression." (PMID 18657901, 2008). "We observed that serum deprivation inhibits RhoA activity and stimulates Rac1 activity and, using dominant negative and constitutively active mutants, that Rac1 and RhoA are antagonistic regulators of tumour cell NHE1 activity." (PMID 15535843, 2004). "We show that the level of RhoA, RhoB, Rac1 and Cdc42 protein is largely enhanced in all tumour samples analysed (n=15) as compared to normal tissues originating from the same individual." (PMID 12237774, 2002). "Ten to twenty per cent of the tumours even showed a >50% reduction in rho mRNA level (i.e. rhoA and rac1)." (PMID 12237774, 2002). "As compared to the normal tissue, about 10–30% of the tumours revealed either enhanced levels of rhoB and rhoC mRNA or even reduced levels of rhoA and rac1 mRNA." (PMID 12237774, 2002).
tumor (continued). "Targeting the Rac1 pathway with small molecule inhibitors (NSC23766, R-ketorolac) reduces survival and motility in resistant cells, inhibits in vivo Rac1 activity, and reduces tumour burden when combined with tamoxifen in a drug-refractory patient derived xenograft model." (PMID 42115169, 2026). "Finally, tumor formation assay in nude mice confirmed that knockdown of RAC1 can reduce the proliferation of A549 cells in vivo." (PMID 39898257, 2025). "NaV1.5 indirectly enhances Rac1 activity by modulating the electrophysiological environment and ion concentrations, while Rac1 directly regulates cell motility, ultimately promoting tumor metastasis." (PMID 39673684, 2025). "At the same time, RAC1 is also closely related to tumor metastasis." (PMID 39898257, 2025). "Notably, in gene-edited cell and animal models, CA has been directly demonstrated to induce tumorigenesis and increase the Rac1-mediated invasion of tumor cells, supporting that CA is a determining factor for tumor progression." (PMID 41443421, 2025). "Additionally, a Rho GTPase activating protein 15 (ARHGAP15) inhibits Rac1 activity and reduces intracellular ROS accumulation, thereby improving the antioxidant capacity of tumor cells during oxidative stress." (PMID 41188920, 2025). "Moreover, the combination of TIPE3 and RAC1 expression exhibited an optimal value in predicting tumor malignancy." (PMID 40904408, 2025). "RAC1 is involved in cytokine/chemokine secretion, endocytic and exocytic vesicle trafficking, and epithelial-mesenchymal transition, functions closely related to tumor microenvironment remodeling." (PMID 41160695, 2025). "It is worth noting that the oncogenic role of RAC1 has been well documented across multiple tumor types, where it functions as a molecular switch integrating signals that regulate cytoskeletal dynamics, migration, invasion, and cross‐talk with the immune microenvironment." (PMID 41498044, 2025). "Furthermore, our research enhances the understanding of RAC1 as a prognostic biomarker and a driver of tumor progression and malignancy." (PMID 39898257, 2025). "Immunogenomic profiling further illuminated the broad impact of RAC1 upregulation on immune checkpoint molecules, tumor infiltrating lymphocytes, and neoantigen loads, suggesting a complex interplay between RAC1‐driven oncogenic signaling and immune surveillance mechanisms." (PMID 41498044, 2025). "Rac1 expression in tumor cells maintains an immunosuppressive state that lowers patient response rates to immune checkpoint inhibitors by positively correlating with Th2 cell and macrophage invasion in the tumor microenvironment." (PMID 41188920, 2025). "Therefore, it is important to delineate the functions of RAC1 splice isoforms under distinct physiopathological contexts including different tumor types." (PMID 40548642, 2025). "Previous studies have demonstrated that members of the TIPE family may influence tumor progression through interactions with RAC1." (PMID 40904408, 2025). "Additionally, proteins associated with neoplasm invasiveness and metastasis (SRC, ALDOA, ACTB, MAPK1, and RAC1) and those mediating epithelial to mesenchymal transition (annexin A1, Hsp27) were upregulated in the LNM group." (PMID 41193833, 2025). "All these results indicated that the TIPE3 and RAC1 promote tumor progression synergistically." (PMID 40904408, 2025). "Importantly, both TIPE3 expression and RAC1 expression were significantly increased in tumor tissues of patients with lymph node metastasis." (PMID 40904408, 2025). "In summary, spatial transcriptomics results indicate that B cells and RAC1 exhibit a mutually exclusive spatial localization relationship, suggesting that RAC1 may impair B cell infiltration in the tumor microenvironment." (PMID 39898257, 2025). "Rac1 has been reported to promote tumor angiogenesis through VEGF." (PMID 39532855, 2024).
tumor (continued). "Some research findings suggest that RAC1 might be involved in regulating the migration, infiltration, and metastasis of tumor cells, subsequently impacting the invasive and metastatic capabilities of tumors." (PMID 38463514, 2024). "Studies have shown that RAC1 can target PAK4‐mediated pyroptosis in tumor cells." (PMID 39224538, 2024). "Increasingly, studies are reporting the role of Rac1 as a potential target for tumor therapy." (PMID 39513883, 2024). "The H3K4me3 occupancy at the TSS of the Rac1 gene in tumor tissues was reduced by ZYZ384." (PMID 39286779, 2024). "TGF-β1 could promote malignant progression of tumor cells by inducing glycolysis, and inhibition of Rac1 inhibits glycolysis and proliferation of BC cells." (PMID 38697993, 2024). "RAC1 has been extensively discussed for its role in promoting proliferation, participating in angiogenesis, facilitating tumor migration and invasion, as well as its involvement in stemness in tumor cells." (PMID 38511143, 2024). "We did not observe differences in tumour growth between vehicle and RK‐treated animals, and a selective Rac1 inhibitor did not ameliorate body weight loss in tumour‐bearing mice, indicating that RK ameliorates CAC independent of Rac1." (PMID 38302863, 2024). "Rac1 is also overrepresented in EVs derived from Mel 270 cells, suggesting that they may preferentially guide the mesenchymal migration from the primary tumor." (PMID 39272836, 2024). "Therefore, β1 integrin induces the reversal of tumor cell polarity by positively regulating RAC1 expression, thereby influencing IMPC prognosis." (PMID 39619442, 2024). "Rac1 is highly expressed in different tumor types and related to poor prognosis." (PMID 39513883, 2024). "One of the important mechanisms in the process of tumor cell invasion and metastasis is the formation of pseudopodia mediated by local aggregation of Rac1 near the cell membrane, and the activity of Rac1 can be regulated by T-lymphoma invasion and metastasis gene 1 (Tiam1)." (PMID 39325938, 2024). "Subsequent inhibition of the RAC1 pathway by EHop-016 further reduced tumor volume and mass." (PMID 38706891, 2024). "All these findings suggest a targeted inhibition of Rac1 by quercetin, which might possibly prevent Rac1 activation and eventually lead to decreased ROS production and prevent tumor cell migration or metastasis." (PMID 38362155, 2024). "Therefore, in this study, we explored the effect of quercetin on Rac1 signaling and tumor cell proliferation." (PMID 38362155, 2024). "Elevated activity of RAC1 could potentially facilitate the infiltration of tumor cells, enabling them to invade surrounding tissues and blood vessels." (PMID 38463514, 2024). "In addition, leptin is able to support the lamellipodia formation and tumor cell invasion through activation of cell division control protein 42 (Cdc42) and Ras-related C3 botulinum toxin substrate 1 (Rac1) in human tumor colorectal cell lines LS174T and HM7." (PMID 37760840, 2023). "Rac1-Scar/Wave-Arp2/3 is of great importance for tumor cell movement." (PMID 37049739, 2023). "It is possible that the cell–cell adhesion may be weak or defective at the tumor boundary, which leads to activation of Rac1 and then promotes cell migration through the ROS–Src–STAT3–vimentin signaling cascade, as proposed in this study." (PMID 36446524, 2023). "Recent studies have shown that Ce6-PDT inhibits tumor cell migration by destroying the structure of actin cytoskeleton and reducing lamellipodium formation, which is closely related to the downregulation of Rac1/PAK1/LIMK1/cofilin." (PMID 37049739, 2023). "Some miRNAs, such as miR-142-3p, inhibit tumor cell migration by restraining Rac1/PAK1." (PMID 37049739, 2023).
tumor (continued). "Moreover, deletion of Rac1 was shown to block tumor initiation but paradoxically exacerbate hepatomegaly induced by Nf2 loss." (PMID 37174657, 2023). "In addition to promoting cytoskeletal polymerization in the cytoplasm to drive tumor cells to extend aggressive pseudopodia and enhance mobility, Rac1 can also play a role through nuclear translocation." (PMID 37049739, 2023). "To determine whether this inter-tumor heterogeneity could be explained by altered expression levels of Rac1 and/or Rac1b in these primary cell lines, we have performed qRT-PCR analysis." (PMID 36599922, 2023). "RAC1 downregulation was shown to reduce metastasis, while RAC1 activation promoted tumor growth." (PMID 37313172, 2023). "Moreover, the tumor samples with amplified RAC1 display a drastic increase of either low gain or high-grade amplification of CBX3 gene." (PMID 37633946, 2023). "Previous studies have demonstrated that emodin could inhibit RhoA and Rock1 on gene and protein levels, and it can also suppress the phosphatidylinositol 3-kinase-Cdc42/Rac1 pathway, resulting in the restrained migratory movement of tumor cells." (PMID 36969843, 2023). "Rac1 regulates lamellipodia formation and migration and invasion of tumor cells." (PMID 37970440, 2023). "Furthermore, the inhibition of Rac1 activity can increase the recognition and cross presentation of DCs to tumor cells." (PMID 37049739, 2023). "In addition, we found that the expression of RAC1, which encodes an important signaling molecule downstream of KRAS pathway, was significantly higher in all three tumor populations." (PMID 37007745, 2023). "Besides tumor invasion and metastasis, Rac1-regulated cell migration also plays an important role in other various physiological and pathological processes." (PMID 37049739, 2023). "Also of interest are the actionable gene mutations acquired and found in tumor progression within nude mice, such as GNAQ, RAC1, and SF3B1." (PMID 37108696, 2023). "In RMS cells, HDAC6 regulates cytoskeletal dynamics through the Rho family GTPase Rac1 to promote tumor cell migration and invasion, and targeting the HDAC6-Rac1 axis may be a therapeutic target for RMS." (PMID 38148899, 2023). "Specifically, during the dissemination, the tumor cells might activate RAC1 to acquire enhanced invasive and migrative abilities to leave the primary tumor, although at a expense of intracellular ROS accumulation." (PMID 36802400, 2023). "Interestingly, the heterologous Rac2-specific 22894 TCR-transduced T cells showed greater efficacy in tumor regression compared to the Rac1-specific TCR 5934." (PMID 36875127, 2023). "Additionally, some of these genes, such as Poli (error-prone polymerase involved in DNA repair), Rac1 (cell growth regulator), and Palb2 (tumor suppressor) were observed on eccDNA in CHO cells." (PMID 36681715, 2023). "Afterward, one study found that TRAIL/DR5 could interact with Rac1/PI3K/AKT and then induce proliferation and metastasis in KRAS‐mutated cells (NSCLC and PDAC tumor cells)." (PMID 37879960, 2023). "Importantly, inhibition of RAC1 contributing to the tumor-suppressive function of miR-22-3p because overexpression of RAC1 restored the migration and invasion ability of NSCLC cells inhibited by miR-22-3p mimics." (PMID 37620594, 2023). "Trio and Kalirin are unique GEFs because they contain two GEF domains, and are proved to regulate F-actin remodeling through activating Rac1, which plays a central role in neurodevelopment, excitatory synaptic transmission and tumor cell migration and invasion." (PMID 37049739, 2023). "Yet another protein that interacts with GLS2, at least in HCC cells, is Ras-related C3 botulinum toxin substrate 1 (Rac1), a member of the Rho GTPase family, involved in the regulation of tumor angiogenesis, invasion, and metastasis; these processes underlie malignant transformation." (PMID 38067269, 2023).